SGK1 (serum/glucocorticoid regulated kinase 1)
Diseases named in the same sentence as SGK1 in open-access papers (continued):
Sharing a sentence is not in itself a finding about the gene and the disease.
cancer (continued). "SGK1 is a crucial Akt‐independent regulator of the PI3K/mTOR signaling pathway which is involved in the regulation of cancer growth, survival, metastasis, autophagy, immunomodulation, cancer stem cells, cell cycle, and induction of therapeutic resistance." (PMID 35106936, 2022). "Considering that several findings have revealed the key roles of ENaC, SGK1, NEDD4-2, and ERK during cancer progression, WNKs may also regulate ENaC in cancer, which needs further explosion." (PMID 36123332, 2022). "Nonsecreting cancers displayed a significant correlation between SGK1 and CTNNB1 mRNA levels (p < 0.001; r = 0.57)." (PMID 35625991, 2022). "MT2A and TRIM31 which were engaged in IFN-γ signaling, CDC6, SGK1 and PTP4A1 genes, presented a homogeneous expression pattern in both test and Validation datasets, although our results were contradictory to other studies in different cancers." (PMID 34249670, 2021). "Recent works indicate that SGK1 and SGK3 have an emerging role in cancer biology sustaining tumor growth in presence of PI3K/AKT inhibition and suggest that these genes could have an oncogenic function." (PMID 32848212, 2020). "Therefore, increased activity of the GC-GR pathway with enhanced induction of Sgk1 and NDRG1 in carcinoma cells play pivotal roles in tumor progression and development of chemo-resistance in patients with ESCC undergoing NAC." (PMID 32106831, 2020). "Interestingly, SGK1 and NDRG1 are known to be down-regulated in human cancers as compared with adjacent normal tissues, and increased expression of both of these genes has been associated with better survival of cancer patients (31, –, 35)." (PMID 30337371, 2018). "In the present study we found that inhibition of the mTORC2 component RICTOR impairs activation of signaling pathways (AKT, SGK1), reduces expression of hypoxia-induced HIF-1α and diminishes secretion of critical cancer-promoting factors involved in stromal recruitment such as VEGF-A and IL-8." (PMID 28445935, 2017). "SGK1 is regulated at different levels by insulin, IGF-1, glucocorticoids and IL-2 and, in turn, modulates survival and proliferative signals in normal and cancer cells." (PMID 26908461, 2016). "Taken together, our data demonstrate the importance of SGK1 as molecular target in cancer therapy and the effectiveness of the SI113-dependent SGK1 inhibition also in GBM treatment, where this drug appears effective as a single agent and also in combination with radiotherapy." (PMID 26908461, 2016). "The cancer related category apoptosis was over-represented with both up- and down-regulated genes, represented by two up-regulated genes (TNS3, EMP1) and five genes down-regulated (DNASE1L2, CXCR4, Gal-7, FKBP5, SGK1)." (PMID 25867603, 2015). "We indicated SGK1 as the possible main mTORC2 effector in CoCSCs, as highlighted by the negative effect on cancer properties following its knockdown." (PMID 24185040, 2013). "This indicates that, at least in these cancer cells, Akt, rather than SGK1, is phosphorylating NDRG1." (PMID 23581296, 2013). "However, SGK1 phosphorylation markedly increases under genotoxic stress, indicating a potential role in promoting survival and resistance to some chemotherapeutics, particularly AKT1 inhibitors in cancer cells." (PMID 37343701, 2023). "In addition, abundant studies presented that TGF-β1 stimulation could upregulate the expression of SGK1 and TOPK in cancer cells to promote EMT." (PMID 37361201, 2023). "Here we report, for the first time, that luteolin has a promotion on apoptosis and autophagy by the SGK1-FOXO3a-BNIP3 pathway in TNBC, which provides novel insights into the exploring of anti-cancer efficacy of luteolin and implies that SGK1 might provide a therapeutic target for TNBC." (PMID 37346292, 2023). "Therefore, in the context of genotoxicity, SGK1 may escape treatments targeting PI3K and AKT1 inhibition in cancer cells, a setting where the small survival advantage conferred by active SGK1 may prove most significant." (PMID 37343701, 2023).
cancer (continued). "Moreover, SGK1 regulates carrier and ion channel through phosphorylation by phosphoinositide-dependent protein kinase-1 (PDPK-1), a signaling intermediate downstream of PI3K, which in turn inhibits EnaC and promotes cancer cell proliferation." (PMID 32070031, 2020). "Interestingly, constitutively active SGK1 did not influence caspase activation in either ECM-attached or -detached cancer cells, suggesting that the effects of SGK1 activation on ATP generation and viability are independent of anoikis." (PMID 33542904, 2020). "Our results suggest that the status of GR, Sgk1, and NDRG1 in ESCC patients undergoing NAC was significantly related to the treatment outcomes and that the GR-Sgk1-NDRG1 pathway in carcinoma cells of ESCC might be involved in the clinical effects of chemotherapy in these patients." (PMID 32106831, 2020). "However, no information is available at present on how modulation of SGK1 expression in cancer is achieved." (PMID 21079778, 2010). "Thus, combining SGK1 inhibition with radiation therapy may provide a powerful novel anti-tumor strategy to combat cancer." (PMID 33542904, 2020). "Since this phenomenon has been observed in cancer cell lines as well as in a noncancerous primary fibroblast cell line, SGK1 and RANBP1 may participate in the general physiologic control of miRNA transport and maturation, increasing the overall impact and biological value of the data." (PMID 28358001, 2017). "We indicate Serum/glucocorticoid-regulated kinase 1 (SGK1) as the possible main mTORC2 effector in CoCSCs, as highlighted by the negative effect on cancer properties following its knockdown." (PMID 24185040, 2013).
tumor (95 papers, 2007 to 2026). "Overexpression of SGK1 is associated with the development of various diseases, including hypertension, obesity, fibrotic diseases, vascular calcification and tumor growth." (PMID 35129051, 2022). "SGK1 is a serine/threonine kinase, and its high expression is closely associated with the development of tumor." (PMID 35129051, 2022). "Excessive expression of Lnc-SGK1 and SGK1 were observed in T cell either within the tumor or peripheral T cells, and furthermore associated with Helicobacter pylori infection and high-salt diet (HSD)." (PMID 26942879, 2016). "Moreover, increased median overall survival associated with increased SGK1 copy number segments may be a reflection of better tumor oxygenation." (PMID 33542904, 2020). "Based on data from GEPIA, our analysis revealed that SGK1 mRNA levels were elevated in tumor tissues compared to normal tissues." (PMID 41326907, 2025). "When SGK1 expressing cells are treated with PI3Kα and PDK1 inhibitors, both AKT and SGK1 are inhibited, inducing tumour regression as a result of FOXO3 activation and mTORC1 inhibition." (PMID 40263319, 2025). "Increased SGK1 expression correlates with increased tumor cell proliferation, invasion, and resistance to apoptosis, contributing to the aggressive nature of tumor cells." (PMID 39940838, 2025). "Tumor development is a multistep process that includes dysregulated energy metabolism, sustained proliferation, apoptosis evasion, and metastasis; GCR, SGK1, and Bcl-2 have been associated with these processes." (PMID 37370761, 2023). "Surprisingly, intraperitoneal injection of GSK-650394 (MCE, China) before modeling resulted in the reduction of CRLM tumor burden in mice, compared with the group of mice with a specific knockout of hepatocytes SGK1." (PMID 36788538, 2023). "SGK1 has also been shown to contribute to tumor development and progression and affect response to treatment." (PMID 37370761, 2023). "The serum- and glucocorticoid-inducible kinase-1 (SGK1) was first discovered in rat tumor cells as a gene, transcriptionally regulated by serum and glucocorticoids and, later, in human as gene upregulated by cell shrinkage." (PMID 35625991, 2022). "SGK1 increases tumor cell survival, adhesiveness, invasiveness, motility, and epithelial to mesenchymal transition." (PMID 35625991, 2022). "SI113 also potentiated and synergized with radiotherapy in tumor killing by reducing MDM2 phosphorylation on serine 166 by SGK1." (PMID 35625991, 2022). "It has been elucidated that SGK1 has a stress-relieving effect that promotes the survival of tumor cells." (PMID 36457711, 2022). "In the present review, we summarized the biological functions of SGK1, focusing on three major roles, i.e., in ion channels, tumor promotion, and immune modulation." (PMID 36457711, 2022). "General alterations in the local/systemic environment, including nutrient availability, hormones, and growth factors, lead to SGK1 induction during tumor progression." (PMID 36457711, 2022). "Other downregulated genes, such as HARS, UBXN1, EBAG9 and SGK1, reduce cytotoxic activity of T lymphocytes, block tumor T cell infiltration, drive T helper type 2 differentiation (TH2) or memory differentiation in CD8 T cells when expression is lost." (PMID 34654826, 2021). "Targeting of SGK1 has the potential to affect the anti-tumor immune response significantly and positively through other mechanisms too." (PMID 33266470, 2020). "A significant positive correlation was detected between post-NAC GR and Sgk1 or NDRG1 status in the tumor tissues (GR versus." (PMID 32106831, 2020). "In summary, PPARβ/δ-deactivated SGK-1 is a novel pathway for inhibiting tumor growth and linking metabolism and liver carcinogenesis together." (PMID 33083492, 2020). "All these studies indicate that SI113 has strong anti-tumor activity, and its selective inhibitory effect on SGK1 is significantly superior to that of the two previously reported inhibitors." (PMID 33542904, 2020).
tumor (continued). "Due to the known tumor-promoting effect of SGK1, the present data suggest that PPARβ/δ-deactivated SGK1 is a novel pathway for inhibiting liver carcinogenesis." (PMID 33083492, 2020). "Recently, it is reported that SGK1 is up-regulated in a variety of tumor types, and involved in the growth, survival, autophagy, and drug resistance of tumor cells." (PMID 33093458, 2020). "On the one hand, these studies indicate that SGK1 plays an important role in the maturation of immune cells and their antitumor effects; on the other hand, SGK1 functions as an oncogene in promoting tumor growth via crosstalk with cytokines." (PMID 33542904, 2020). "In most tumor types, the expression of SGK1 is dysregulated, although SGK1 upregulation or downregulation has been differentially observed, subject to the particular tumor type." (PMID 33542904, 2020). "SGK1 functions as an oncogene in some tumors and as a tumor suppressor in others, which suggests that the function of SGK1 is tumor- and cellular context-dependent." (PMID 33542904, 2020). "Treatment with the Src inhibitor AZD0530 resulted in a modest but significant reduction in tumor growth, while the effect of SGK1 was more marked." (PMID 30655532, 2019). "SGK1 promotes survival, invasiveness, motility, epithelial to mesenchymal transition, and adhesiveness of tumor cells." (PMID 31815093, 2019). "When analyzing spleen cells from tumor-bearing mice at day 15–17 p.i., we detected similarly significant changes in Tnfα, Ifnγ, and Nos2 expression and a significant increase in Sgk1 expression." (PMID 31214164, 2019). "In human clinical trials, long-term administration of a Class 1 PI3Kα inhibitor (BYL719) resulted in metastatic tumours in some patients that became resistant to the inhibitor by up-regulating SGK1." (PMID 29150437, 2018). "In mice, T-cell specific deletion of SGK1 results in the animals being more capable of rejecting tumours." (PMID 29301334, 2018). "The in vivo antimetastatic effects of SGK1 inhibition in PCa was determined in a tumor-transplant mouse model." (PMID 29609629, 2018). "Particularly, SGK1-overexpressing PCa xenografts displayed accelerated castrate-resistant tumor initiation, supporting a role for SGK1-mediated PCa progression." (PMID 29609629, 2018). "Strikingly, down-regulation of akt-2 or sgk-1, like daf-2, suppressed germline hyperplasia in shc-1;akt-1 animals, indicating that the activity of DAF-2, AKT-2 or SGK-1 in this context contributed to germline tumor formation." (PMID 28549065, 2017). "SGK1 plays an important role in regulating ion transport as well as cell metabolism and tumor growth, and is activated via PI3K, PDK1 and mTORC2." (PMID 28825630, 2017). "We observed that only the combination of BYL719 and SGK1-inh reduced tumor burden and phosphorylation of S6, 4EBP1, and NDRG1." (PMID 27451907, 2016). "Lnc-SGK1 and SGK1 transcription was significantly higher in GC tumor infiltration cells (TILS) than adjacent normal tissue and peripheral blood mononuclear cells (PBMCs)." (PMID 26942879, 2016). "It has been shown that the transcription factor FOXO1 acts as a tumor suppresser, and can be phosphorylated by Akt and SGK1 protein kinases." (PMID 25749387, 2015). "The SGK1 kinase is pivotal in signal transduction pathways operating in cell transformation and tumor progression." (PMID 26462020, 2015). "SGK1 stimulates cell proliferation and confers cell survival and thus actively participates in regulation of tumor growth." (PMID 25015419, 2014). "Invivo however, FACS of tumor cells of 3 mice after the end of the experiment showed a marked decrease in CD44 expression with SGK-1 inhibition." (PMID 25485633, 2014). "SGK-1 inhibition suppresses tumor growth, and in combination with systemic cisplatin exceeds the effect of cisplatin alone." (PMID 25485633, 2014). "Finding that an Akt inhibitor robustly suppresses NDRG1 phosphorylation would indicate that the tumour has high Akt, but low SGK1, activity." (PMID 23581296, 2013).
tumor (continued). "This also emphasizes the key role that SGK1 activity can play in driving the expansion of tumour cells." (PMID 23581296, 2013). "In contrast, if administration of an Akt inhibitor failed to suppress NDRG1 phosphorylation, this would be a sign that SGK1 activity was elevated, and that the tumours would be likely to be resistant to Akt inhibitors." (PMID 23581296, 2013). "Knock-down of sgk-1 significantly reduced number of the germ cells, suggesting SGK-1 contributes to proliferation of the germline tumor in shc-1;Is[daf-16::gfp] animals." (PMID 22916022, 2012). "We observed CpG methylation only in the smaller and more distal CpG island in the promoter region of SGK1 in both normal and tumour samples of colonic origin." (PMID 21079778, 2010). "Serum- and glucocorticoid-induced protein kinase 1 (SGK1) was originally identified as an immediate early gene transcriptionally induced by serum or glucocorticoids in tumor cells." (PMID 17938736, 2007). "Due to the limited effect of SGK1 on leukemic cell differentiation, we examined if the kinase could be involved in another tumor-suppressive process." (PMID 40613901, 2025). "Since WT1 represses the SGK1 promoter, SGK1 might act as a tumor suppressor in this context by inducing the differentiation of leukemic cells." (PMID 40613901, 2025). "Growing evidence has also indicated that SGK1 does play a crucial role in tumor EMT and metastasis." (PMID 40500263, 2025). "The involvement of SGK1 in the differentiation process in leukemic cells could suggest a tumor suppressor behavior." (PMID 40613901, 2025). "WT1 and SGK1 can act as oncogenes or tumor suppressors, depending on the context." (PMID 40613901, 2025). "Furthermore, knockdown of hepatocyte SGK1 significantly slowed IR-related tumor growth and prolonged the survival of mice." (PMID 36788538, 2023). "In addition to promoting tumor growth, SGK1 signaling contributes to GC resistance, consistent with its aberrant upregulation found in GC-resistant ALL." (PMID 37345151, 2023). "Furthermore, SGK1 phosphorylation of N-MYC downstream regulated gene 1 (NDRG1) promotes tumor cell growth and tissue extravasation." (PMID 37143725, 2023). "SGK1 phosphorylates the protein ubiquitin ligase Nedd4-2, then binds with the protein 14-3-3, and blocks its ability to ubiquinate Orai-1, resulting in increased Orai1 activity, which confers survival of tumor cells." (PMID 37345151, 2023). "In summary, our study demonstrated that activation of IL-6/STAT3/SAA signaling by hepatocyte SGK1 in response to IR promotes the formation of a pre-metastatic niche in the liver of CRC, and that tumor-associated NETs and PMN-MDSCs participate in the formation of CRC in an SGK1-dependent manner." (PMID 36788538, 2023). "Moreover, an increasing number of studies have suggested that SGK1 can regulate the functions of immune cells including T helper cells, and regulatory T cells in the tumor microenvironment." (PMID 35711939, 2022). "In addition, SGK-1 expression and activation contribute to tumor invasiveness, metastasis, and resistance to treatment." (PMID 35048019, 2021). "Additionally, overexpression of mTORC2 target SGK1 is correlates with tumor growth and invasion in various cancers." (PMID 35250965, 2021). "All considered, the targeting of SGK1 could potentially eliminate tumor cell-intrinsic pro-tumorigenic effects by ablating its corticosteroid-induced upregulation and signaling." (PMID 33266470, 2020). "However, the Sgk1 score significantly increased following NAC in patients with a low histopathological tumor regression grade (P = 0.0021)." (PMID 32106831, 2020). "In addition, higher SGK1 expression was observed in 1090 tumor samples of invasive breast cancer from The Cancer Genome Atlas (TCGA)." (PMID 33542904, 2020). "However, based on what is currently known, SGK1 inactivation can result in anti-oncogenic effects both on tumor cells and on the immune microenvironment." (PMID 33266470, 2020).